RNU6-1195P (RNA, U6 small nuclear 1195, pseudogene)
Gene: Small nuclear RNA gene on chromosome 4 (41,113,942 to 41,114,045, forward strand). Ensembl gene ENSG00000207198.
Homologues: Orthologues: chimpanzee U6 (98% identical), rabbit U6 (90% identical), rat U6 (90% identical), mouse Gm25698 (88% identical), rabbit U6 (88% identical), macaque U6 (86% identical), rat U6 (84% identical). Paralogues in human: RNU6-33P (91% identical), RNU6-1 (90% identical), RNU6-2 (90% identical), RNU6-3P (90% identical), RNU6-4P (90% identical), RNU6-5P (90% identical), RNU6-6P (90% identical), RNU6-9 (90% identical), RNU6-12P (89% identical), RNU6-13P (89% identical), RNU6-17P (89% identical), RNU6-18P (89% identical), and 1288 more.